CCL20 (C-C motif chemokine ligand 20)
Diseases named in the same sentence as CCL20 in open-access papers (continued):
Sharing a sentence is not in itself a finding about the gene and the disease.
tumor (continued). "In addition, the chemokine receptor CCR6 [which binds to the chemokine CC ligand 20 (CCL20) that is present in many malignant pleural effusions of lung cancer patients] is highly expressed on Th17 cells thus further facilitating their recruitment to sites of tumor growth and inflammation." (PMID 23533029, 2013). "CCL20 and CXCL1 are involved in tumor growth and TNFAIP6 can regulate the growth of smooth muscle cells." (PMID 23028973, 2012). "Injection of recombinant mouse CCL20 into CRC promoted tumor development with a marked recruitment of Treg-cells in wild-type mice, and stimulated tumor growth by directly activating CMT93 cells in CCR6−/− mice." (PMID 21559338, 2011). "Thus, CCL20 mediates Tregs trafficking in vitro and may recruit Tregs into the tumor." (PMID 21935436, 2011). "Here we show that intra-tumoral levels of CCL20 were elevated as compared to tumor adjacent lung tissue and that CCR6 positive immune cell infiltrates were found in the tumor parenchyma." (PMID 21949768, 2011). "Others and we have shown that CCL20/CCR6 auto-signaling occurs in prostatic cancerous cells and that tumor CCR6 expression correlates with disease aggressiveness, thus marking intra-tumoral CCL20/CCR6 interactions as a pro-carcinogenic axis." (PMID 21949768, 2011). "EpCAM (p = 0.0001), IL8 (p = 0.0003), CCL4/MIP-1β (p = 0.0026), CCL20/MIP-3α (p = 0.039) and TIMP1 (p = 0.0017) tissue protein levels were significantly different (Mann Whitney U test) between tumours versus AN & PN." (PMID 21092330, 2010). "CFD/Adipsin median levels were found to be lower in tumours compared to the levels in PN and AN (p = 0.0324), while CXCL5/ENA78, CCL20/MIP-3α, IGFBP3, SPP1/OPN and TIMP1 were increased in PN and tumours relative to AN, with higher levels seen in tumours." (PMID 21092330, 2010). "Our recent results provide a novel mechanism for CXCR4-mediated tumor growth and metastasis and establish a functional link between CXCR4/CXCL12 and CCR6/CCL20 pathways in tumor development." (PMID 19340288, 2009). "Both in vitro and in vivo experiments suggest that CCL20 has a chemotactic effect on Treg cells, and although the CCL20 OE group recruited more lymphocytes, the tumor growth was not restricted." (PMID 41399390, 2026). "At the same time, although CCL20 induced more lymphocyte infiltration in animal experiments, it did not limit tumor growth." (PMID 41399390, 2026). "Upon intratumoral injection into multiple murine tumor models (A20, MC38, and EO771), the bacteria proliferated within the tumor and underwent density‐dependent lysis, releasing CXCL16^K42A and CCL20 to selectively recruit CD8+ T cells and precursor dendritic cells, respectively." (PMID 40878391, 2025). "Knockdown of Ccl20 and Cxcl3 notably decreased tumor growth in nude mice, but there was no substantial difference between the short hairpin Cxcl3 (sh-Cxcl3) and sh-Ccl20 groups." (PMID 40179015, 2025). "Consistently, no obvious differences in CCL20 mRNA levels in tumor tissues or in human HCC cells from different groups." (PMID 39755756, 2025). "Of note, CCL20 was shown to be upregulated in HNC patients, contributing to tumor progression." (PMID 40573439, 2025). "Notably, HER2-CXCR5-CCR6-CAR T cells demonstrated significantly enhanced tumor infiltration compared to conventional HER2-CAR T cells, attributable to their triple-targeting capacity for tumor sites co-expressing HER2, CXCL13, and CCL20." (PMID 40764989, 2025). "Although gene expression analysis in OPMD tissues was limited by the small sample size available from diagnostic biopsies, we employed the Gene Expression database of Normal and Tumor tissues 2 (GENT2) to objectively evaluate tissue expression levels for CPLANE1 and CCL20." (PMID 40869423, 2025).
tumor (continued). "Mechanistically, radiotherapy-induced tumor cell–derived microparticles containing dsDNA activated the cGAS-STING/NF-κB signaling pathway in macrophages, upregulating the expression of the chemokine CCL20, which was critical for γδ T cell recruitment." (PMID 41055972, 2025). "It is widely acknowledged that chemokines secreted by tumor cells such as CCL2, CCL5, CCL7, CCL20, CXCL2, CXCL8 and CXCL12 significantly contribute to the recruitment of monocytes and macrophages during neoplastic transformation, among which CCL2 plays a key role in TAM recruitment." (PMID 40380196, 2025). "CCL20 production led to recruitment of γδ T cells, a unique population of innate-like T cells that respond to nonclassical antigens, including tumor neoantigens." (PMID 41392975, 2025). "At the molecular level, the expression of Il4, Il17a, and Il33, but not that of Tslp, Ccl20 or Ccl27a, was dramatically lower in the skin lesions of the IL-1R antibody-treated SSKO mice than in those of their IgG-treated SSKO littermates." (PMID 39939818, 2025). "Additional chemokines and growth factors, such as TGF‐α, CCL4, CCL20, IL‐17A, IL‐2RB, and FGF‐23, further underscore the multifaceted interplay between inflammation and tumor biology through pathways ranging from proliferation and angiogenesis to immune cell recruitment." (PMID 41458898, 2025). "A recent explored the effect and molecular mechanisms of cathepsin D (Cat D) in the tumor microenvironment and showed that Cat D-mediated expression of CCL20 in cancer cells can promote polarization of M2 macrophages enhancing epithelial mesenchymal transition (EMT) and tumor metastasis." (PMID 39985603, 2025). "The biomarkers identified in the T3 subtype include MSLN and CD117 (KIT), which have been reported in TC and other advanced tumor cells, and CCL20 which has not been reported in TC." (PMID 39258580, 2024). "Furthermore, RANKL/RANK signaling stimulated C-C motif chemokine ligand 20 (CCL20) production by CRC cells, leading to Treg recruitment and boosting tumor stemness and malignant progression." (PMID 38902257, 2024). "Additionally, a differential expression of the cytokine genes CCL2, CCL20, TGFB1, and TGFB2; the transcription factor gene IRF4; and the receptor genes CCR2, IL10RB, TGFBR1, and TGFBR2 was identified in tumor tissue and vestibular nerve tissue." (PMID 39272860, 2024). "In vitro, Juz- or Gem/Juz-treated KPC tumor cells secreted significantly more macrophage-chemoattractant cytokines, e.g., CCL2, CCL20, and CXCL2, whilst Juz- and Gem/Juz-treated macrophages (MH-S) secreted cytokines of the M1 phenotype, e.g., IL6, TNF-α, and IL12." (PMID 39723364, 2024). "Studies have shown that IL-17A can promote ESCC tumor cells to produce more chemokines CCL2, CCL20, and CXCL13, enhance B cell migration, or enhance IgG-mediated antibody and complement-mediated cytotoxicity of B cells to tumor cells to inhibit tumor development." (PMID 39906741, 2024). "No studies are currently available on the anti-leukemic properties of CCL20 in AML, but it can be speculated that CCL20 secreted by AML cells might promote the migration of cytotoxic lymphocytes, which have anti-tumor effects." (PMID 39409868, 2024). "Additionally, many chemokines or cytokines, such as CCL20, CXCL5, and CXCL13 (Cluster 9), had significantly different expression levels between the two populations, which indicates differences in the tumor microenvironment." (PMID 38166892, 2024). "Th17 cells also strongly induce the expression of CCL20 in tumor tissue, stimulating the mobilization of dendritic cells and other leukocytes to the tumor site, where they activate CD8+ T cells to suppress tumor growth." (PMID 39534095, 2024). "CCL20 is a cytokine that can promote Treg cell infiltration, and the CCR6-CCL20 axis regulated Tregs migrate into the tumor microenvironment, thereby leading to tumor progression and poor prognosis in patients with HCC." (PMID 37180150, 2023).
tumor (continued). "We screened top ten upregulated genes in chemokine signaling pathways and the top fifty up-regulated genes in all sequenced genes, and consistently found CXCL2 and its receptor CXCR2 were significantly upregulated in CCL20-modulated PMN-MDSCs and tumor cells, respectively." (PMID 36859354, 2023). "On the contrary, analysis of cellular interactions by CellChat revealed that M1 macrophages were stimulated by complement from CCL20- but not CCL20+ tumor cells." (PMID 37398643, 2023). "Although we did not obsereved faster tumor growth in CCL20-OE mice, we did find out a significant worse survival in CCL20-OE mice." (PMID 37183243, 2023). "Moreover, the tumor cell-derived CXCL6, CXCL2, and CCL20, TAM-derived CXCL9/CXCL10, and the stromal cell-derived CXCL12 also contributed to the accumulation of tissue-resident CD103+CD8+TILs in the TME." (PMID 37024870, 2023). "However, the same cells increased the recruitment of neutrophils through interleukin 8 (IL-8) secretion and attracted cytotoxic CCR5+CCR6+CD8+T cells into tumor tissue through CCL5 and CCL20 production." (PMID 37185750, 2023). "Furthermore, Th17 cells were found to be responsible for CCL5 and CCL20 secretion, which are known to recruit CD8+ T cells (CCR5+ CCR6-) in the intraepithelial regions of the tumor." (PMID 37185750, 2023). "To investigate whether CCL20 promoted cancer progression via remodeling TME, we established tumor-bearing Balb/c and C57BL/6N mouse models, which were orthotopically transplanted with pSIN-/CCL20-overexpressing 4T1 and Py8119 cells, respectively." (PMID 36859354, 2023). "In addition, it was noteworthy that CCL20 not only affected prognosis and differentiation of LUAD but also led to poor histologic grade of tumor cells." (PMID 35480896, 2022). "Other studies have demonstrated that CCL20 may also attract T helper 17 (Th17) lymphocytes in EC, thereby recruiting DCs to promote the activation of CD8+ T cells and enhance anti-tumor immunity." (PMID 36119033, 2022). "We hypothesized that Tc17 cells may migrate to the tumor tissue, secrete CCL20 to recruit MoDCs, and then the activated DCs secrete CXCL10 to induce CD8+ T cell tumor infiltration, leading to inhibition of tumor growth." (PMID 35459193, 2022). "Indeed, under cisplatin treatment, there is a production of CCL20 and IL-1β by murine lung and breast cancer cells, which triggers the recruitment of the CCR6+ type 3 innate lymphoid cells (ILC3) at the tumor site." (PMID 36429101, 2022). "According to the clustering results, C1q+ TAMs, SPP1+ TAMs, and CCL20+IL1B+ macrophages were substantially more abundant in tumor tissue than in non-malignant colorectal tissues." (PMID 36172359, 2022). "In addition, others found that CCL20 secreted by tumor cells is one of the main chemokines in TME, and lncRNA u50535 can regulate CCL20 expression and affect CCL20/CCR6/ERK signaling, leading to CRC tumorigenesis." (PMID 35574420, 2022). "Inflammation in liver tissues may bring about higher CCL20 and LCN2; further production of them by tumor cells would be the main source in HCC sera." (PMID 35308139, 2022). "CCL20 expression was significantly higher in F. nucleatum positive tumor tissues compared to F. nucleatum negative tissues." (PMID 34761269, 2022). "In addition, the RORγt agonist promoted Type 17 T cell migration by upregulating CCL20 and CCR6 expression, and Type 17 T cell tumor infiltration." (PMID 35459193, 2022). "As revealed by our gene set enrichment analysis, many factors being elevated in the serum of LHMS patients, e.g., the chemokines CCL3, CCL20, MCP-3, and MCP-4, are involved in chemotaxis, migration, and recruitment of monocytic and lymphocytic immune cells into the tumor." (PMID 36230528, 2022). "CCR6 is a specific receptor for CCL20, and CCR6 expression has also been shown on tumor cells." (PMID 36045408, 2022).
tumor (continued). "CCL20 is produced by TAM, as well as tumor and stromal cells." (PMID 33924428, 2021). "Although the authors did not provide a regulatory mechanism of CCL20 induced TAMs in angiogenesis, TAMs have been demonstrated to promote angiogenesis by supplying tumor cells with angiogenic factors." (PMID 34569432, 2021). "In addition, CCL20 also attracts other immune system cells that express its receptor CCR6, such as Th17, which contribute to a pro-tumor TME in various cancers." (PMID 35048056, 2021). "Tumor-associated macrophages (TAMs) acquired M2 phenotype could produce cytokines, including IL-6, IL-10, and C-C motif chemokine ligand 20 (CCL20), to reduce anti-tumor immune response and support tumor growth." (PMID 32723346, 2020). "Moreover, the ALA-PALE region was characterized by an overexpression, with respect to both ALA+ and ALA−derived GASC, of CCL20, CSF3 and IL1B (magenta box), suggesting the possible importance of these three genes in the infiltrating front of the tumor." (PMID 33066172, 2020). "Lu and colleagues found that the anti-tumor efficacy of Th9 subsets was independent of mast cells but was highly correlated with CCL20, the ligand of CCR6, derived from bronchial and alveolar epithelial cells." (PMID 32508847, 2020). "Tumor cytokines’ dynamics indicate that as the tumor grows, HMGB1, IFN-γ and μ1 (IL-6, IL-17, IL-21, IL-22) increase in density, but TGF-β and μ2 (IL-10, CCL20) stay relatively constant." (PMID 33291412, 2020). "Moreover, circulating levels of CCL20 in HCC patients before and after tumor resection were significantly increased, in comparison to the HG, as well as in CCA patients at T0, which presented a partial recovery after tumor resection." (PMID 32256215, 2020). "In this study, we found EBNA1 increased infiltration of Tregs in tumor microenvironment through converting naïve T cell into Tregs via upregulate TGF‐β1, upregulated CCL20 increased Tregs migration, and polarized‐M2 macrophage converted naïve T cells into Tregs." (PMID 32573058, 2020). "In addition, IL-9 boosted the production of CCL20 in lung tissue, leading to the recruitment of CCR6+ DCs and CCR6+ CD8+ T cells to the tumor bed." (PMID 32508847, 2020). "Interestingly, these pathways are utilized by a series of chemokines and their receptors, such as CCL20/CCR6, CCL25/CCR9, CXCL1/CXCR2, CXCL8/CXCR1-2, CXCL12/CXCR4, and CX3CL1/CX3CR1, to inhibit apoptosis and promote tumor cell growth and proliferation." (PMID 31991604, 2020). "Since CCL20 showed the most prominent Ras-dependent upregulation among all tested chemokines, and previous findings supported a role for CXCL14 and CCL27 in tumour-immune surveillance, we decided to investigate further the role of CCL20 within the tumour microenvironment." (PMID 32601464, 2020). "Given that the vasculature plays a major role in regulating tumour growth as well as metastasis, we investigated whether microvascular endothelial cells express CCR6, the corresponding receptor for CCL20, on their surface." (PMID 32601464, 2020). "Pharmacological inhibition of CCL20 and CSF-1 or the genetic silencing of FOXO1 might serve as an excellent candidate to suppress tumor progression and improve prognosis." (PMID 33052231, 2020). "Other chemokines, for example, CCL7, CCL20, CXCL1, and CXCL17, demonstrate similar expression patterns and may also be important contributors to MØ tumor infiltration, MØ differentiation, and a more aggressive phenotype." (PMID 30451357, 2019). "Moreover, BrCa cells secrete CCL20, which recruits CCR6 expressing immune cells in the tumor vicinity." (PMID 30850664, 2019). "Together, these findings suggest that the CCL20/CCR6 axis might facilitate infiltration of Th17 cell in NSCLC and promote tumor progression." (PMID 31921642, 2019).
tumor (continued). "A recent analysis of 20 different cytokines and chemokines (some also included here) in culture supernatants harvested from HNSCC tumor tissue-derived cell suspensions, showed, in accordance with the present study, high tumor related levels of CXCL9, CXCL10, and CCL20 and decreased levels of CCL5." (PMID 29587383, 2018). "Our results in vivo suggested that CCL20 silencing could significantly improve the therapeutic effect of docetaxel and inhibit tumor growth in MDA-MB-231 tumor model." (PMID 30052635, 2018). "Exosomes derived from heat-stressed tumor cells (HS-TEX) which contain chemokines, such as CCL2, CCL3, CCL4, CCL5, and CCL20, could chemoattract and activate dendritic cells (DC) and T cells more potently." (PMID 29164149, 2017). "Chemokines in the omental tumor tissues revealed some changes as follows: 1) the decreased levels in CCL26, CCL28, CXCL1-3, CXCL8 and CXCL16; 2) the increased level in CCL24; and 3) the conserved level in CCL20 compared to the parental cells." (PMID 27723802, 2016). "We initially found that NSCLC tumour tissues markedly overexpressed CCL20 in comparison with normal lung samples." (PMID 26968871, 2016). "IL-17A could stimulate ESCC tumor cells to produce much more chemokines, such as CCL2, CCL20 and CXCL13." (PMID 26942702, 2016). "Interestingly, the expression of CCL20 and CXCL16 by tumor cells has been reported to be correlated with prognosis and infiltration of lymphocytes into cancer tissues." (PMID 27517754, 2016). "Gene expression analysis in pretumor mammary glands showed that all growth factors and chemokines observed to be elevated before tumor development in continuous HFD mice at 13 weeks of age (i.e., Tgfa, Ccl1, Ccl17, Ccl20, Ccl22, and Tgfb1) were elevated in LFD-HFD mammary glands at this time." (PMID 26526858, 2015). "Correspondingly, level of CCL20 in the tumor tissues was significantly higher than that in non-tumor and normal control tissues, and strongly positively associated with Th17 cells." (PMID 25768730, 2015). "MMP1, IL24 and CCL20 are mRNAs that are well studied for their role in cancer; however the remaining mRNAs have not been characterized for their potential role in HNSCC tumorigenesis and/or tumor progression and warrant further study." (PMID 26498364, 2015). "EPCs participating in neovascularization have also been reported in HCC, in which myeloid-derived EPCs (colony forming unit-endothelial cells) as early EPCs highly express CCR6 and are mobilized by the ligand CCL20 produced by HCC cells for migration and invasion of tumor stroma to form vasculature." (PMID 25110692, 2014). "High intra-tumoral levels of CCL20 result in the accumulation of immature CCR6+ DCs within the tumor bed, whereas high peri-tumoral levels of CCL19 promote the accumulation of mature CCR7+ DCs preferentially to the tumor margin." (PMID 24339824, 2013). "First, a strongly positive correlation was observed between the number of FoxP3+ Tregs and CCL20 expression in tumor tissue (P<0.001), but not in non-tumor tissue (P = 0.894)." (PMID 21935436, 2011). "Consistent with real-time PCR, the CCL20 expression in tumor tissue was significantly stronger than that in non-tumor (integrated optical density/hpf, 14529 vs. 4969, P<0.001) and normal liver tissue (vs. 1534, P = 0.001)." (PMID 21935436, 2011). "Most interestingly, we observed that recombinant mouse CCL20 stimulated CMT93 CRC cell growth by directly activating CCR6 on tumor cells in the absence of CCR6+ TIL in CCR6−/− mice." (PMID 21559338, 2011). "Functional validation via in vitro chemotaxis assays and in vivo xenograft models demonstrates that CXCL10 overexpression suppresses tumor growth by enhancing effector immune cell infiltration, while CCL20 promotes Treg accumulation without impeding tumor progression." (PMID 41399390, 2026).